ULBP2 (UL16 binding protein 2)
Description:
Binds and activates the KLRK1/NKG2D receptor, mediating natural killer cell cytotoxicity.
Synonyms: NKG2DL2; N2DL2; RAET1H; ALCAN-alpha
Tractability: Small molecule: a structure with a bound ligand is known. Antibody: UniProt places it where antibodies can reach, with high confidence; its Gene Ontology location is reachable by antibodies, with high confidence; UniProt predicts a signal peptide or a membrane-spanning region; the Human Protein Atlas places it where antibodies can reach. PROTAC: ubiquitination databases record sites on it.
Gene: Protein-coding gene on chromosome 6 (149,942,014 to 149,949,235, forward strand). Ensembl gene ENSG00000131015.
Subcellular location: Cell membrane; Endoplasmic reticulum; Secreted
Subcellular location (Human Protein Atlas): Plasma membrane; Vesicles; Predicted to be secreted
Pathways (Reactome):
Metabolism of proteins: Post-translational modification: synthesis of GPI-anchored proteins
Gene Ontology:
Molecular function: GPI anchor binding; natural killer cell lectin-like receptor binding; protein binding; receptor ligand activity
Biological process: natural killer cell activation; natural killer cell mediated cytotoxicity; antigen processing and presentation of endogenous peptide antigen via MHC class I via ER pathway, TAP-independent; antigen processing and presentation of endogenous peptide antigen via MHC class Ib; positive regulation of T cell mediated cytotoxicity; signal transduction
Cellular component: cell surface; endoplasmic reticulum; extracellular region; plasma membrane; external side of plasma membrane
Genetic constraint (gnomAD): Loss-of-function variants: 21 observed, 21.38 expected, observed/expected ratio (o/e) 0.98, 90% interval 0.7 to 1.41. The upper end of that interval is the gene's LOEUF score, 1.41, which puts it in group 5 of 6, group 1 being the genes least tolerant of losing a copy. Missense variants: 248 observed, 249.74 expected, observed/expected ratio (o/e) 0.99, 90% interval 0.89 to 1.1. Synonymous variants: 81 observed, 91.72 expected, observed/expected ratio (o/e) 0.88, 90% interval 0.74 to 1.06.
Homologues: Orthologues: pig ULBP1 (39% identical), mouse Ulbp1 (24% identical), zebrafish mhc1laa (15% identical), zebrafish mhc1lda (14% identical), zebrafish mhc1lga (14% identical), zebrafish mhc1lfa (14% identical), tropical clawed frog mhc1-uea (13% identical), zebrafish mhc1lja (13% identical), zebrafish mhc1lla (13% identical), zebrafish mhc1lca (12% identical), zebrafish mhc1lba (11% identical), zebrafish si:dkey-52p2.5 (11% identical). Paralogues in human: RAET1L (94% identical), RAET1G (88% identical), ULBP1 (59% identical), ULBP3 (53% identical), RAET1E (33% identical), HLA-E (26% identical), HLA-B (24% identical), HLA-C (24% identical), HLA-A (24% identical), HLA-F (23% identical), HLA-G (22% identical), HFE (22% identical), and 10 more.
Diseases named in the same sentence as ULBP2 in open-access papers:
ULBP2 is named in the same sentence as 70 diseases in open-access papers, as found by Europe PMC text mining. Sharing a sentence is not in itself a finding about the gene and the disease. The quoted sentences say what the papers report.
melanoma (24 papers, 2011 to 2025). A malignant, usually aggressive tumor composed of atypical, neoplastic melanocytes. "Expression of ULBP2, including elevated levels of the shed form, was also associated with worsened outcomes in both melanoma and B-cell chronic lymphocytic leukaemia (CLL)." (PMID 37626965, 2023). "Previous report showed that high levels of soluble ULBP2 in sera were associated with poor disease prognosis in melanoma patients, suggesting that soluble ULBP2 is involved in tumor immune evasion." (PMID 27049654, 2016). "In particular, ULBP2 has been identified as a predictive marker for cancer prognosis, and the levels of ULBP2 in sera from melanoma patients are strongly associated with tumor load." (PMID 24614922, 2014). "For example, the concentration of ULBP2 in serum appears to be associated with poor survival in melanoma, B-cell chronic lymphocytic leukemia and lung cancer patients, and therefore it can be a marker for tumor load." (PMID 24614922, 2014). "Thus, soluble ULBP2 was associated with lower survival in melanoma patients." (PMID 26779186, 2015). "We had previously reported that CD4+ T cell depletion suppressed the growth of mock tumors in a B16F10 melanoma model, whereas this effect was lost in tumors expressing ULBP2." (PMID 40558520, 2025). "In our recent study using a syngeneic mouse model with B16F10 melanoma cells stably expressing ULBP2, we demonstrated that surface ULBP2 promotes tumor growth by suppressing NK cell-mediated immunity through NKG2D." (PMID 40558520, 2025). "In this study, we investigated the role of ULBP2 in modulating anti-tumor immunity using murine melanoma cell lines engineered to stably express surface-expressed or soluble ULBP2." (PMID 40243581, 2025). "Subcutaneous transplantation of ULBP2-expressing melanoma cells into syngeneic mice resulted in accelerated tumor growth, mediated by surface-expressed ULBP2, through the suppression of NKG2D-dependent immune responses." (PMID 40243581, 2025). "An elevation of soluble ULBP2 in the serum has been reported as a poor prognostic factor in patients with non-small cell lung cancer, melanoma, and pancreatic cancer." (PMID 40243581, 2025). "While both soluble ULBP2 and MICA were elevated in melanoma patients, only soluble ULBP2 correlated with worsened survival." (PMID 37626965, 2023). "There is a study suggesting that CEACAM1, particularly the CEACAM1-3S isoform, was able to induce enhanced expression of the NKG2D ligands MICA and ULBP2 on the surface of melanoma cells, which in turn contributed to NK cell-mediated cytolysis of tumor cells." (PMID 36712923, 2023). "This work also shows that BRAFi and MEKi, as solo or combined treatments in vitro, decreased soluble MICA, MICB and ULBP2 in supernatants from BRAF-mutant melanoma cells." (PMID 36726591, 2022). "They discovered that ULBP2 was highly expressed in melanoma tissues and that the high concentration of sULBP2 was significantly associated with disease progression, tumor load and reduction in overall survival." (PMID 33909599, 2021). "Overexpression of miR-34a and miR-34c in melanoma cells downregulates the ability of NK cells to recognize melanoma cells by targeting ULBP2." (PMID 34827646, 2021). "Metastatic melanoma cells escape immune surveillance by enhancing ULBP2 shedding, which makes soluble ligands detectable in serum from melanoma patients." (PMID 30866509, 2019). "Soluble NKG2D ligands MICA and ULBP2 are released by melanoma cells and can down-regulate the expression of NKG2D on effector cells." (PMID 26779186, 2015). "Although ULBP2 has been reported as a tissue and serum prognostic marker for ovarian cancer and melanoma, respectively, we believe that ULBP2 still has potential as a relatively specific and useful serum test for PC diagnosis." (PMID 21625447, 2011).
melanoma (continued). "Supporting this hypothesis, clinical studies have reported that elevated serum ULBP2 levels are correlated with poor outcomes in patients with melanoma treated with immune checkpoint inhibitors." (PMID 40558520, 2025). "The UL16 binding protein 2 and 3 (Ulbp2/3), carcinoembryonic antigen‐related cell adhesion molecule 1 (Ceacam1) and galectin 9 (LgalS9) were identified as possible regulators of melanoma cell resistance to NK‐cell cytotoxicity." (PMID 41078003, 2025). "Inhibition of BRAF with vemurafenib led to reduced MICA and ULBP2 expression by melanoma cells." (PMID 37626965, 2023). "Interestingly, soluble ULBP2 has been identified as an independent predictor of prognosis in melanoma patients." (PMID 30871206, 2019). "MICA/B expression was observed at a higher frequency than ULBP2 on melanoma metastasis." (PMID 26779186, 2015). "Using murine melanoma cell lines (B16F10 and B16BL6) engineered to stably express ULBP2, we found that these cells successfully engrafted into syngeneic C57BL/6 mice without causing immune rejection." (PMID 40243581, 2025). "To evaluate the role of ULBP2 in anti-tumor immunity and tumor progression, we generated B16F10 murine melanoma cells stably expressing ULBP2 (B16F10-ULBP2)." (PMID 40243581, 2025). "For example, the treatment of human melanoma cells with IFN-γ reduces MICA levels, and TGF-β downregulates the transcription of MICA, ULBP2, and ULBP4 in human malignant gliomas." (PMID 37603573, 2023). "The cluster binds the 3′UTR region of ULBP2 (UL16 binding protein 2), a stress-induced ligand of NKG2D, promoting immune escape by enhancing its shedding from melanoma cells, which are detectable in serum samples from melanoma patients." (PMID 33203119, 2020). "miR-34a and miR-34c act as tumor suppressive miRNAs controlling the expression of ULBP2, by directly targeting the ULBP2 3′-UTR, in human malignant melanoma." (PMID 32316552, 2020). "miR-34a and miR-34c have been shown to enhance NK-cell killing activity against melanoma cells by targeting the UL16 binding protein 2, while miR-34 mimics led to down-regulation of ULBP2, diminishing tumor cell recognition by NK cells." (PMID 32604720, 2020). "Nevertheless, the treatment of melanoma cells with 1 mM VPA has been shown to induce only MICA, MICB and ULBP-2, mediated by the ERK pathway, which is also consistent with our results using Panc89 and PC-3 tumor cells." (PMID 30972064, 2019). "Expression of CEACAM1-4L on the surface of melanoma cells reduces the expression of MICA, ULBP2, CD155 and CD112 via matrix metalloproteinase (MMP)-mediated shedding of these ligands, resulting in escape of NK cell mediated killing." (PMID 30871206, 2019). "Therefore, to bridge this gap, we generated murine melanoma cell lines (B16F10 and B16BL6) stably expressing ULBP2 and evaluated the effects of ULBP2 on tumor progression using a syngeneic transplantation mouse model." (PMID 40243581, 2025). "In consequence, recent in vitro data has shown that, under pressure of the BRAF inhibitor Vemurafenib (PLX4032), human melanoma cells downregulate B7-H6, MICA, ULBP2 and the DNAM-1 ligand CD155, and upregulate MHC class I expression, in order to escape NK-cell mediated tumor cell recognition." (PMID 30871206, 2019). "Melanoma patients benefit from the expression of CEACAM1-3S as a consequence of enhanced expression of the NKG2D ligands MICA, ULBP2 and DNAM-1 ligand CD155 on the surface of melanoma cells, thus presenting these cells as targets for NK cell mediated cytolysis." (PMID 30871206, 2019). "Similarly to human ovarian cancer cells, human melanoma cells have been reported to express NKG2D receptor ligands such as MICA and ULBP2." (PMID 27349385, 2016). "Additionally, analysis of patient data sets only displayed minor expression of ULBP2/3 among all melanoma cell clusters (data not shown)." (PMID 41078003, 2025).
melanoma (continued). "Additionally, VSVΔM51 infection inhibited endogenous MICA/B and ULBP-2 surface expression on Jurkat T-cells (data not shown) and constitutive MICA/B surface expression on the two melanoma cell lines, FM-86 and FM-78." (PMID 21857986, 2011).
pancreatic cancer (17 papers, 2011 to 2025). "ULBP2, a ligand for the natural killer group 2D receptor, has been previously implicated in tumor immune escape and prognosis across various cancers, including lung cancer, pancreatic cancer, and lymphoma." (PMID 40640957, 2025). "Therefore, ULBP2 is hypothesized to be associated with the malignant transformation of pancreatic cancer." (PMID 27602753, 2016). "Previous studies have shown that ULBP2 is expressed in many types of human cancers, including breast cancer, pancreatic cancer, colon cancer, and ovarian cancer." (PMID 40775202, 2025). "ULBP2 expression increased in serum and correlated with tumour progression in pancreatic cancer patients relative to healthy individuals, with similar observations in lung cancer patients." (PMID 36649303, 2023). "In ovarian, head and neck, and pancreatic cancers, the expression of NKR ligands B7-H6, ULBP2, RAET1E, and death receptor TRAIL-R were associated with a poorer prognosis." (PMID 36839682, 2023). "Meanwhile, ULBP2 has been shown to be a prognosis indicator for several cancers, such as lung cancer and pancreatic cancer." (PMID 35938006, 2022). "Recent studies have found that elevated expression of ULBP2 is an indicator of poor prognosis in ovarian and pancreatic cancer." (PMID 33216733, 2020). "In the analysis of pancreatic cancer, researchers have proved that a high level of soluble ULBP2 is deemed an independent indicator for OS." (PMID 29653552, 2018). "Serum levels of ULBP2 in pancreatic cancer patients were also found to correlate significantly with shorter overall survival and poor prognosis." (PMID 27602753, 2016). "The present study sheds light on previously unrecognized effects of gemcitabine on tumor immune response, modulating ADAM10 and ULBP2 shedding, thus suggesting its use in chemoimmunotherapy against human pancreatic cancer." (PMID 27602753, 2016). "ULBP2 shedding is thought to be a principal mechanism by which tumor cells escape from NKG2D-mediated immune surveillance in pancreatic cancer." (PMID 27602753, 2016). "More importantly, an analysis of the area under the ROC curve showed that ULBP2 was superior to CA 19-9 in discriminating patients with early-stage pancreatic cancer from healthy controls." (PMID 21625447, 2011). "In addition, ULBP2 has been shown to be associated with invasive liver tumorigenesis, and soluble ULBP2 derived from pancreatic cancer cells can reduce the cytotoxicity of NK cells." (PMID 36313765, 2022). "Indeed, gemcitabine treatment impaired ULBP2 shedding through downregulation of ADAM10 in pancreatic cancer." (PMID 28993779, 2017). "The aim of the present case-control study was to compare the diagnostic value of ULBP2, MIC-1 and carbohydrate antigen 19-9 (CA19-9) in 359 serum samples, consisting of 152 cases of PC, 20 cases of pre-pancreatic cancer, 91 cases of chronic pancreatitis (CP) and 96 normal controls (NC)." (PMID 25295097, 2014). "Collectively, our results indicate that ULBP2 may represent a novel and useful serum biomarker for pancreatic cancer primary screening." (PMID 21625447, 2011). "However, evaluation of ULBP2 as a pancreatic cancer marker will require large-scale counter-screening, particularly using serum samples from pancreatitis patients." (PMID 21625447, 2011). "However, pancreatic cancer cells can secrete ULBP2 and reduce the cytotoxicity of NK cells, thereby mediating immune escape and promoting tumor progression, and multivariate regression analysis indicated that ULBP2 was an important independent factor related to poor overall survival." (PMID 34266418, 2021). "ULBP2 may influence the survival of pancreatic cancer patients." (PMID 34266418, 2021). "Decrease of sULBP2 and increase of membrane-bound ULBP2 thus promote NK cells activation and may improve the antitumor effect against pancreatic cancer, which will be further confirmed by studies on tissues of pancreatic cancer patients." (PMID 27602753, 2016).
pancreatic cancer (continued). "Thus, ULBP2 may represent a novel and useful serum biomarker for primary screening for pancreatic cancer." (PMID 21625447, 2011). "In this study, gemcitabine upregulated the expression of MICB, ULBP1, ULBP2/5/6, ULBP3, and PVR in pancreatic cancer cell lines." (PMID 37169953, 2023). "In particular, valproic acid (VPA) has been reported to upregulate MICA/B with a mechanism dependent on PI3K/Akt pathway in pancreatic cancer cells, while the involvement of ERK in MICA/B and ULBP2 upregulation in response to VPA has been shown in MM cells." (PMID 28993779, 2017). "In fact, NKG2D ligand (MICA/B and ULBP-2) gene expression was remarkably induced with 2.5 mM VPA both on malignant (pancreatic carcinoma cells Panc89 and prostate carcinoma cells PC-3) and non-malignant cells (PBMC and γδ T cells)." (PMID 30972064, 2019). "Our data showed that the level of soluble ULBP2 (sULBP2), a ligand of NKG2D receptor, decreased in the supernatants of pancreatic cancer cell lines when gemcitabine was added, and sULBP2 level correlated with NK92 cells cytotoxicity to pancreatic cancer cell lines." (PMID 27602753, 2016). "The results indirectly confirmed that the effect of gemcitabine on pancreatic cancer may be related to ADAM10 and ULBP2." (PMID 27602753, 2016). "Treatment of various pancreatic cancer cell lines with the nucleotide analog gemcitabine inhibited ULBP-2 ectodomain shedding through the suppression of ADAM10, thus leading to an enhancement of NK cell cytotoxicity that was strictly dependent on NKG2D/ULBP-2 interaction." (PMID 32269567, 2020). "Thus, out of six different epigenetic modifiers tested, only HDAC inhibitor VPA increased cell surface expression and/or release of MICA, MICB and ULBP-2 from the pancreatic carcinoma and prostate carcinoma cell lines irrespective of their allelic MICA variation." (PMID 30972064, 2019).